AHNAK2 (AHNAK nucleoprotein 2)
Diseases named in the same sentence as AHNAK2 in open-access papers (continued):
Sharing a sentence is not in itself a finding about the gene and the disease.
tumor (continued). "Among the DEGs between distinct pyroptosis-related subtypes, AHNAK2 knockdown was previously reported to activate the Wnt pathway and correlated with tumor immune cell infiltration while its role in BC is rarely reported." (PMID 35558555, 2022). "A recent study has demonstrated that the expression of AHNAK2 is related to TIICs (tumor-infiltrating immune cells)." (PMID 35359393, 2022). "As part of the ISG family, overexpression of NDC80, NPAS2, and AHNAK2 changed tumor microenvironment." (PMID 35813478, 2022). "The majority of work with AHNAK2 has been done in oncology, with some convincing evidence of a pro-oncogenic role, in contrast to the contradictory tumour suppressor and oncogenic roles of AHNAK." (PMID 35158796, 2022). "AHNAK nucleoprotein 2 (AHNAK2) was reported to have pro-tumor growth effects across multiple cancers, while its role in tumor immunity was unclear." (PMID 35359393, 2022). "A survival analysis suggested that AHNAK2 overexpression predicts poor overall survival and tumor malignancy." (PMID 35558555, 2022). "We therefore assessed the function of AHNAK2 on cell migration and invasion using wound healing and trans-well assaysin vitro and evaluated the function of AHNAK2 on tumor metastasis using xenograft modelin vivo." (PMID 36017889, 2022). "Together, these results suggested that AHNAK2 regulates tumor progression by mediating DNA replication and anoikis." (PMID 36017889, 2022). "Sh#2-AHNAK2 was selected for subsequent xenograft assay as it was more effective.In vivo, two cell lines derived xenograft (CDX) models were used to study the role of AHNAK2 in adenocarcinoma tumor progression." (PMID 36017889, 2022). "In tumor tissues, AHNAK2 was variously observed in the cytoplasm and/or plasma and nuclear membrane of tumor cells." (PMID 33918555, 2021). "TISIDB showed that the high expression of AHNAK2 in pan-cancer tended to be accompanied by an advanced tumor stage and short overall survival (OS)." (PMID 32966238, 2020). "AHNAK2 expression was significantly positively correlated with tumor progression and poor overall survival (OS) in pan-cancer patients." (PMID 32966238, 2020). "The expression of AHNAK2 was upregulated in tumor samples and correlated with poor prognosis in LUAD patients." (PMID 32904605, 2020). "Through ESTIMATE analysis, we found that high AHNAK2 expression indicates high degrees of immune and stromal cell infiltration and low tumor purity in the PTC microenvironment." (PMID 32966238, 2020). "In this investigation, we detected AHNAK2 levels in pathological specimens and databases from Clinical Proteomic Tumor Analysis Consortium (CPTAC), The Cancer Genome Atlas (TCGA), Gene Expression Omnibus (GEO), and The Genotype-Tissue Expression (GTEx)." (PMID 32904605, 2020). "The analysis of AHNAK2 protein level in CPTAC-LUAD showed that compared with normal tissues, AHNAK2 was highly expressed in tumor samples." (PMID 32904605, 2020). "Notably, the knockout of the AHNAK2 gene showed a diminished tumor progression, further confirming AHNAK2’s role in tumorigenesis." (PMID 41471728, 2025). "In case 2, we observed all 5 tumor samples and non-tumor samples had mutations in many of the same genes such as AHNAK2, ZFHX3, KMT2C and MAP3K1." (PMID 41471728, 2025). "Notably, the function of AHNAK2 within the PAAD tumor microenvironment (TME) has been scarcely documented in the literature." (PMID 41465903, 2025). "For patients who underwent radical cystectomy and have high AHNAK2 expression in tumor tissues, their disease-free survival and cancer-specific survival were significantly shortened, and multivariate analysis confirmed that AHNAK2 was an independent poor prognostic factor." (PMID 41019085, 2025). "Pan-cancer analysis revealed significant upregulation of AHNAK2 across most tumor tissues." (PMID 39593730, 2024). "Single-cell sequencing data showed a similar trend in AHNAK2 expression over tumor evolution." (PMID 39593730, 2024).
tumor (continued). "One study indicated that SMYD2 can directly methylate AHNAK as well as multiple sites in the CRU region of AHNAK2, which may be involved in regulating cell adhesion, cell signaling, and tumor cell migration and invasion." (PMID 38033502, 2023). "Downregulation of AHNAK2 inhibits lipid synthesis and thus affects tumor cell metabolism." (PMID 38033502, 2023). "We further tried to address whether AHNAK2 can be used as a biomarker only for adenocarcinomas and whether it functions in the tumor progression of adenocarcinomas." (PMID 36017889, 2022). "MUC4 and AHNAK2 were the most frequent differential genes in invasive disease compared with that in in situ; they may play the role of promoting tumor invasion." (PMID 36091120, 2022). "We thus posit that the dysfunction of AHNAK2 may contribute to tumor immunity and improved outcomes in ICI-treated NSCLC." (PMID 35359393, 2022). "However, the biology of the protein is unclear, with early evidence linking HIF-1α mediated EMT in hypoxia and the PI3K/AKT/mTOR pathway with AHNAK2 as possible modes to increase tumour proliferation, migration, and survival." (PMID 35158796, 2022). "This primary in silico work provided strong evidence that AHNAK2 may have a link with tumour growth, oncogenesis, and disease progression in ccRCC, which is further elucidated through in vitro and in vivo experiments." (PMID 35158796, 2022). "Further comprehensive analysis of GSEA results revealed that AHNAK2 promoted tumour cell adhesion, cell–substrate junction formation, and regulation of the actin cytoskeleton and inhibited amino acid metabolism, cell mitochondrial respiration, and oxidative phosphorylation." (PMID 35158796, 2022). "AHNAK2 can also carry out its pro-tumor role via activating immune microenvironment." (PMID 36091120, 2022). "AHNAK2 performs a tumor regulatory function involving multi-faceted processes." (PMID 36091120, 2022). "Our study found that although the expression levels of AHNAK2 differ in various tumors, they are significantly positively correlated with tumor progression and short OS in pan-cancer patients, indicating that AHNAK2 also has universal prognostic value in pan-cancer." (PMID 32966238, 2020). "Moreover, we found significant connections between AHNAK2 methylation and clinical parameters such as tumor purity, stage, T classification, N classification and histological type." (PMID 32966238, 2020). "Moreover, we detected the expression of mRNA in TCGA-LUAD, GEO (GSE72094, GSE 26939), and GTEx datasets; the mRNA levels of AHNAK2 were also upregulated in tumor tissues." (PMID 32904605, 2020). "The interaction between AHNAK2 and TGFB1 could potentially contribute to the establishment of an immunosuppressive microenvironment, facilitating tumor progression and highlighting AHNAK2 as a potential target for cancer-related research and therapeutic interventions." (PMID 41465903, 2025). "We further found that AHNAK2 deleterious mutation (del-AHNAK2mut) possessed better predictive function in NSCLC than non-deleterious AHNAK2 mutation (PFS, OS, log-rank p < 0.05), potentially associated with stronger tumor immunogenicity and an activated immune microenvironment." (PMID 35359393, 2022). "Interestingly, in each patient from our study, one tumor was conformed with deleterious AHNAK2 mutation and the other was conformed without AHNAK2 mutation." (PMID 35359393, 2022). "This stemness-associated signature integrates developmental drivers such as PTPRH, AHNAK2, PCDH7, metabolic regulators CPS1, SFTPB, and hypoxia-responsive factors such as TCN1, TMPRSS11E, reflecting the multifaceted nature of OSA-induced tumor evolution." (PMID 41584048, 2026).
tumor (continued). "Using a mouse model of metastatic TNBC, we identified four new CTC surface markers, AHNAK2, CAVIN1, ODR4, and TRIML2, which specifically stain tumor cells." (PMID 41543394, 2026). "AHNAK2 and XKR6 are involved in cell adhesion and signal transduction, potentially regulating interactions between tumor cells and immune cells." (PMID 41479783, 2025). "AHNAK2 is a large molecular nuclear protein with a molecular weight exceeding 600 kDa, belonging to the AHNAK protein family, regulating tumor progression by activating signaling pathways such as ERK, MAPK, Wnt, and MEK, as well as promoting EMT." (PMID 41019085, 2025). "Further, the prognostic performance of immune subtype is superior to that of traditional tumor markers (VHL, AHNAK2, and CDKN2A) in ccRCC patients." (PMID 37315301, 2023). "Taken together, these findings show that PI3K/Akt signaling is a common tumor-promoting pathway for S100A16 and AHNAK2." (PMID 37833982, 2023). "Lentiviral-mediated knockdown of AHNAK2 reduced cell proliferation, growth, and migration in the immortalised CAKI-1 (ccRCC) cell line (p < 0.01) and inhibited xenograft tumour growth in nude mice." (PMID 35158796, 2022). "So far, it seems that there is a strong link between AHNAK2 and PDAC, with evidence to suggest a link between AHNAK2 expression and tumour grade, prognosis, survival, and oncogenesis, with a strong potential to be part of a diagnostic or predictive biomarker." (PMID 35158796, 2022). "There seems to be a correlation between AHNAK2 and epithelial cancers that requires further investigation, particularly AHNAK2’s relationship with PDAC, as it is an aggressive tumour with limited treatment options." (PMID 35158796, 2022). "Analysis of tumour-immune cell infiltration using the tumour immune estimation resource (TIMER) and the CIBERSORT function showed a positive correlation between AHNAK2 expression and B-cell, CD4+ T cell, macrophage, neutrophil, and dendritic cell infiltration." (PMID 35158796, 2022). "The experimental results confirmed that ADH4 and AHNAK2 were significantly upregulated, while MMAA and DMBT1 were downregulated analogously in tumor tissues or recurrent tissues compared with controls." (PMID 35847888, 2022). "Pan-cancer analyses revealed the functional roles of AHNAK2 in the epithelial-mesenchymal transition (EMT), which plays a key role as a tumor promoter by allowing epithelial cells to gain a range of mesenchymal characteristics." (PMID 33918555, 2021). "Multivariate Cox regression analysis suggested that AHNAK2 could become an independent predictor after adjusting for other parameters, including age, gender, American Joint Committee on Cancer (AJCC) stage, BRAF mutations, RAS mutations and tumor mutation burden (TMB) (PFS as the ending indicator)." (PMID 32966238, 2020). "Nevertheless, poorly differentiated cell lines mimicked upregulated expression of genes (in tumours) such as CAV1, COL4A1, and novel candidates such as TSPAN5, TENM2, C15orf48, PLAU, AHNAK2, FAM129A, PLAU and platelet-specific phosphofructokinase (PFKP)." (PMID 30176945, 2018). "Another meta-analysis approach based on PDAC datasets allowed the identification of a 5 genes classifier signature (TMPRSS4, AHNAK2, POSTN, ECT2, SERPINB5) with 95% sensitivity and 89% specificity in discriminating PDAC from non-tumor samples." (PMID 30236127, 2018). "Our limited analysis has shown that neither age, tumoral AHNAK2 expression or tumour stage influence AHNAK2 levels in plasma." (PMID 39849106, 2025). "Notably, the most dysregulated gene, AHNAK nucleoprotein 2 (AHNAK2), exhibited increased levels during tumor cell development in the control scenario, while SERPING1 expression decreased during the later stages of pseudotime." (PMID 39962118, 2025). "From the molecular mechanism perspective, the expression of AHNAK2 in the tumor hypoxic microenvironment is regulated by HIF-1α, which may drive tumor progression by inducing EMT and enhancing tumor stem cell characteristics." (PMID 41019085, 2025).
tumor (continued). "Lastly, presence of extra-cellular matrix proteins, abundantly seen in the tumour micro-environment of PDAC, could also enhance cellular process co-localisation of AHNAK2 with Cortactin." (PMID 39849106, 2025). "In non-neoplastic tissues, AHNAK2 was observed in the cytoplasm of smooth muscle cells in the muscular layer, peripheral nerve cells, endothelial cells, macrophages, and tumor stromal fibroblasts." (PMID 33918555, 2021). "AHNAK plays a key role in regulating blood-brain barrier formation, cell structure and migration, cardiac calcium channel signaling, and tumor metastasis, while there is a relative lack of functional research on AHNAK2, a homologue of AHNAK." (PMID 32904605, 2020). "A 5-gene PDAC classifier (TMPRSS4, AHNAK2, POSTN, ECT2, SERPINB5) achieved on average 95% sensitivity and 89% specificity in discriminating PDAC from non-tumor samples in four training sets and similar performance (sensitivity = 94%, specificity = 89.6%) in five independent validation datasets." (PMID 26993610, 2016). "The gene mutations of the brain metastasis were not present in the extracranial tumours and, moreover, we identified three private gene mutations (PIK3CB M819L, PIK3CB Q818H, AHNAK2 L5292V) exclusively present in the meningeal lesion." (PMID 26554728, 2015). "Consistently, AHNAK2, a protein which was previously proposed as a PDAC prognosis marker with unknown function, was positive in tumor area of 25/28 patients, compared with only 1/28 patients positive at adjacent normal area (X-squared = 37.979, degree of freedom = 1, p value = 7.1 × 10−10)." (PMID 38280869, 2024). "Interestingly, the 5-gene classifier contained only genes labeled related to activated stroma (POSTN) and basal-like tumor (AHNAK2, SERPINB5, TMPRSS4), and excluded classical tumor-like genes, which might explain the inferior classification performance." (PMID 29675033, 2018). "However, AHNAK2 seems to exist more as an activator of signal pathways, which could promote the activation of PI3K/AKT, MEK/ERK and NF-κB signals and induce EMT, invasion and migration of tumor cells." (PMID 38033502, 2023). "AHNAK2 is needed for the non-classical secretion of FGF1 that can bind to fibroblast growth factor receptors (FGFR), exerting an effect on cell growth, tissue repair, tumour growth, invasion, and various cell survival related activities." (PMID 35158796, 2022). "The PCR and Western blot analysis results suggested that CA12 and AHNAK2 were significantly upregulated, while MMAA and DMBT1 were downregulated in the tumor sample compared with adjacent tissues, and in non-recurrent samples compared with non-recurrent samples in COAD." (PMID 35847888, 2022).
cancer (42 papers, 2016 to 2026). A tumor composed of atypical neoplastic, often pleomorphic cells that invade other tissues. "For instance, AHNAK2 and CAVIN1 have been linked to proliferation and migration in different cancers and AHNAK2 and ODR4 were identified as potential biomarkers for adenocarcinomas." (PMID 41543394, 2026). "AHNAK2 is a gene that is still being understood, but has been shown to be closely associated with cancer biology." (PMID 41471728, 2025). "AHNAK2 is abnormally highly expressed in numerous cancers and is closely associated with poor prognosis." (PMID 41019085, 2025). "Our findings suggest that the addition of epitopes derived from AHNAK2 variants will improve personalized peptide vaccine efficacy and serve as the starting line for the development of a pan-cancer vaccine." (PMID 41471728, 2025). "High-frequency mutation of AHNAK2 correlated with poor prognosis of cancer patients, promoting epithelial–mesenchymal transition and activating oncogenic pathways, such as MAPK, Wnt, and MEK signaling pathways." (PMID 39830210, 2024). "We visualized the top 15 mutated genes among differentiated genes in epithelial cells and cancer cells, and the mutation rate of AHNAK2 reached 10 %." (PMID 38765128, 2024). "Using univariate regression analysis, we examined the associations of AHNAK and AHNAK2 with the prognosis of 33 cancers by R language." (PMID 38033502, 2023). "AHNAK2 upregulation is correlated significantly with advanced grades of various cancers and was associated with EMT." (PMID 37476073, 2023). "To further assess the predictive value of deleterious AHNAK2 mutations, we explored another pan-cancer immunotherapy cohort as an independent external validation." (PMID 35359393, 2022). "AHNAK2 in cancer has considerable promise for future studies, especially as it is not related to mutation but rather to the normal function of AHNAK2." (PMID 35158796, 2022). "Collectively, these results imply that elevated AHNAK2 expression might be linked to an increased predisposition to cancer." (PMID 41465903, 2025). "Taken together, these in silico analyses indicate that high AHNAK2 expression may be associated with poor survival due to its role in the invasive capability of cancer cells, which is potentiated by hypoxia." (PMID 39849106, 2025). "As a diagnostic marker, AHNAK2 could immunohistochemically differentiate between inflammatory changes and carcinoma in situ (CIS)." (PMID 33918555, 2021). "Subsequently, we explored the relationship between AHNAK2 expression and the expression of immunomodulators across various human cancer types using the TISIDB database." (PMID 41465903, 2025). "We investigated the expression levels of the key gene AHNAK2 and its correlation with chemotherapeutic agents in 60 human cancer cell lines from the NCI-60 panel." (PMID 41465903, 2025). "In case 1, we observed 13, 17, 32, 10, and 5 AHNAK2 variants within our CIN1, CIN3, cancer stage IA1, cancer stage IIB, and control samples, respectively." (PMID 41471728, 2025). "The AHNAK2 gene is highly expressed in various cancer tissues and promotes LUAD progression through multiple signaling pathways." (PMID 39593730, 2024). "It turned out that AHNAK and AHNAK2 were significantly differentially expressed in cancer and paraneoplastic tissues of some tumors." (PMID 38033502, 2023). "Contribution of the expression of AHNAK2 to survival by univariate Cox regression analysis in cancers." (PMID 38033502, 2023). "To further confirm functional proteins associated with drug efficacy and response, we identified 19 genes as cancer-related genes (CRGs) in PCa, whereas 15 were overlapped DEP/Gs, and four (TTN, NBPF14, AHNAK2, COL1A1) were the top mutated genes in PCMR." (PMID 37121942, 2023). "cBioPortal mRNA analysis shows a strong correlation between high AHNAK2 expression and different cancers." (PMID 35158796, 2022).